HOXA10 (homeobox A10)
Diseases named in the same sentence as HOXA10 in open-access papers (continued):
Sharing a sentence is not in itself a finding about the gene and the disease.
glioblastoma (11 papers, 2014 to 2020). The most malignant astrocytic tumor (WHO grade IV). "HOXA10 was associated with temozolomide resistance through regulation of the homologous recombinant DNA repair pathway in glioblastoma cell lines." (PMID 31568655, 2020). "Since HOXA10 expression is associated with therapy resistance of glioblastoma, upregulation of snoRNA by RA, alone or in combination with THAL, might contribute to decreasing therapy resistance to chemo- or radiotherapy." (PMID 26362268, 2015). "High expression of HOXA10 was predictive of resistance of temozolomide treatment in glioblastoma through regulation of the homologous recombinant DNA repair pathway." (PMID 31568655, 2020). "MLL can directly activate the homeobox gene HOXA10 and contributes to the tumorigenic potential of glioblastoma stem cells." (PMID 27160082, 2016). "Among the ten most upregulated genes, five (SNORA20, SNORA71A, SNORA23, SNORA3, SNORA68) were recently found to be downregulated by HOXA10 in LN18 glioblastoma cells." (PMID 26362268, 2015). "We identify the CpG island of the HOXA10 alternative promoter that appears to escape hypermethylation in the HOX-high glioblastoma." (PMID 25622821, 2015). "Two glioblastoma cell lines with different MGMT statuses were used to test the augmented anticancer effect of temozolomide with HOXA10 inhibition." (PMID 25061500, 2014). "In the present study, we investigated the mechanism of HOXA10 regarding its role in temozolomide resistance using glioblastoma cell lines and tested the therapeutic implication of temozolomide resistance in conjunction with MGMT status." (PMID 25061500, 2014). "The mechanism of HR pathway regulation by HOXA10 harbors another target mechanism for overcoming temozolomide resistance in glioblastoma patients." (PMID 25061500, 2014). "The self-renewal properties and the activated DNA repair system (e. g., HOXA10) might be responsible for the relapse of the recurrent G1 glioblastomas after resection and adjuvant treatment." (PMID 26466313, 2015). "Additionally, several studies have reported that HOXA9 and HOXA10 can serve as predictive biomarkers of poor survival in glioblastoma multiforme (GBM)." (PMID 32296636, 2020). "HOXA10 has been known to involve in homologous recombinant DNA repair pathway, playing a key role in TMZ resistance in glioblastomas." (PMID 26466313, 2015). "Also, we used tool ‘GEO profiles’ of NCBI to search the expression of two homeobox genes (HOXA5 and HOXA10) and two cadherin genes (PCDHA1 and PCDHB13) in different grades of the glioblastoma." (PMID 27160082, 2016). "In particular, HOXA10 expression was recently shown to be regulated by the Trithorax protein mixed lineage leukemia (MLL), resulting in the activation of HOXA10-target genes that contribute to the tumorigenic potential of glioblastoma stem cells." (PMID 25762636, 2015).
glioma (11 papers, 2011 to 2023). A benign or malignant brain and spinal cord tumor that arises from glial cells (astrocytes, oligodendrocytes, ependymal cells). "Meanwhile, another research about high-grade pediatric glioma strengthened the prognostic value of HOXA10 via Kaplan–Meier analysis in 78 samples." (PMID 37351805, 2023). "Some studies have shown that the high expression level of HOXA10 is related to the malignancy of gliomas, poor prognosis, and tumor immunity." (PMID 37759912, 2023). "It is worth noting here that HOXA10 has been reported to be an oncogene in glioma before and this finding is consistent with the conclusion of our study, which suggests the research value of HOXA10 in the regulation of glioma progression in the future." (PMID 34294084, 2021). "In the last step, a series of rescue assays were designed to confirm the interaction among PSMA3-AS1, miR-411-3p and HOXA10 in glioma." (PMID 34294084, 2021). "Back to this current research, HOXA10 silencing was proven to depress glioma cell proliferation while inducing cell apoptosis, indicating that HOXA10 played as an oncogene in glioma." (PMID 34294084, 2021). "Subsequently, EdU and colony formation assays were implemented to examine cell proliferation after HOXA10 was knocked down in glioma cells, which turned out that HOXA10 knockdown effectively depressed cell proliferation." (PMID 34294084, 2021). "The methylation and expression of HOXA10 has been functionally connected to the stem cell pattern of glioma cells." (PMID 30322114, 2018). "Multiple HOX genes have been shown to be overexpressed in glioma and confer prognostic value, while HOXA10 has been shown to play a role in drug resistance and tumor recurrence." (PMID 28055976, 2017). "By western-blot analysis, HOXA9, HOXA11, and HOXA13 were dramatically up-regulated in GBM, and HOXA10 merely showed a slight increase in high-grade glioma." (PMID 26356815, 2015). "Many reports have identified HOXA9 and HOXA10 signatures in GBM, and high expression levels of HOXA9 and HOXA10 were predictive of shorter survival in some high-grade glioma patients." (PMID 26356815, 2015). "Recently, it has been reported that HOXA9 decreases apoptosis and increases cell proliferation in glioma cells by epigenetic control and the expression of HOXA10 in GBM-derived spheres." (PMID 21600039, 2011). "At present, the research on HOXA10 in gliomas is still limited." (PMID 37759912, 2023). "In conclusion, this study initially uncovered that PSMA3-AS1 could serve as an oncogene in glioma progression by sponging miR-411-3p to regulate HOXA10." (PMID 34294084, 2021). "PSMA3-AS1 stimulated glioma progression via the miR-411-3p/HOXA10 pathway, which might offer a novel insight for the therapy and treatment of glioma." (PMID 34294084, 2021). "To conclude, PSMA3-AS1 promotes glioma progression through modulating the miR-411-3p/HOXA10 axis." (PMID 34294084, 2021). "Inversely, silencing PSMA3-AS1 accelerated glioma cell apoptosis, while this effect could be countervailed by miR-411-3p knockdown or HOXA10 up-regulation." (PMID 34294084, 2021). "Specifically, high expression of HOXA9 and HOXA10 have been reported in human glioma cell lines." (PMID 31073965, 2019). "Furthermore, PSMA3-AS1 could act as a competitive endogenous RNA (ceRNA) for miR-411-3p to regulate HOXA10 and thus affecting glioma progression." (PMID 34294084, 2021). "Since HOXA9 and HOXA10 have been associated with temozolomide resistance in pediatric glioma, we hypothesized that MLL proteins might also have a functional role in pediatric glioma." (PMID 34381018, 2021). "Besides, through JC-1, flow cytometry and TUNEL assays, we discovered that down-regulation of HOXA10 could enhance cell apoptosis in glioma cells." (PMID 34294084, 2021).
glioma (continued). "According to recent publications, the stem cell signature of diffuse astrocytoma is quite different from the other two glioma subtypes, indicating that HOXA10 may be a potential biomarker for the identification of diffuse astrocytoma cells and validating the efficacy and accuracy of our prediction." (PMID 30322114, 2018). "In the present study, we found that HOXA5, HOXA7, HOXA10, HOXC4 and HOXC6 are prognostic markers in glioma patients." (PMID 28055976, 2017). "In the present study, we first analyzed the expression of HOXA9, HOXA10, HOXA11, and HOXA13 protein in glioma tissues; we then further analyzed the expression of HOXA9, HOXA10, HOXA11, HOXA13, and HOTTIP mRNA in the same samples." (PMID 26356815, 2015). "In order to explore the role of the 5′ HOXA genes in gliomas, we first measured the expression of HOXA9, HOXA10, HOXA11, and HOXA13 protein in 66 gliomas specimens of different grades." (PMID 26356815, 2015). "In glioma, PSMA3-AS1 promoted proliferation by affecting the miR-411-3p/HOXA10 axis." (PMID 37403106, 2023). "Importantly, we found that CD133 expression in glioma was highly correlated with the expression of HOX gene stem cell factors (HOXA5, HOXA7, HOXA10, HOXC4 and HOXC6)." (PMID 28055976, 2017). "In addition, the expression of HOXA10 and HOXA13 increased in the WHO IV gliomas compared to the WHO II & III gliomas, and the mRNA expression of HOTTIP increased from WHO II gliomas to WHO IV gliomas." (PMID 26356815, 2015). "Analysis of individual loci in glioma samples using strand‐oriented RNA‐seq data supported the hypothesis that transcription can initiate from these H3K4me3‐marked TSS, embedded in methylated areas (see, for instance, HOXA5 and HOXA10)." (PMID 33720519, 2021). "Similarly, and as previously proposed, a read‐through transcript of HOXA10 and HOXA9 might account for the detected HOXA9 transcription signal because the canonical CGI/promoter of this gene was DNA‐methylated and H3K4me3‐depleted in IDHwt glioma samples." (PMID 33720519, 2021).
lung carcinoma (11 papers, 2016 to 2025). "In head and neck squamous cell cancer, lncRNA LINC00520 enhanced radioresistance via miR-195/HOXA10, while In lung cancer, lncRNA LINC00483 upregulated radioresistance via miR-144/HOXA10." (PMID 35600868, 2022). "Next, the downstream mechanism of HOXA10 regulating lung cancer proliferation, migration, and invasion was further investigated." (PMID 33596966, 2021). "The results further validated the importance of competitive relationships among HOXA11-AS, IGF2BP3, and HOXA10 in lung cancer progression." (PMID 33614509, 2020). "A study demonstrated that PCG HOXA10 overexpressed in lung cancer frequently and was involved in the pathogenesis of lung cancer." (PMID 29069717, 2017). "HOXA10 has been reported to be increased in human lung cancer cell lines and lung tumor tissues with respect to normal lung." (PMID 27081700, 2016). "Currently, some studies have demonstrated the association among HOXA10, IGF2BP3, and lung cancer." (PMID 33614509, 2020). "Through data analysis applied to lung cancer prognosis, ten pathways related to LUSC prognosis were found, as well as the key biomarkers closely related to these pathways, such as HOXA10, hsa-mir-182, and LINC02544." (PMID 39411374, 2024). "This also upregulates HOXA10, MMP‐2, and MMP‐9, contributing to migration of lung cancer cells and ultimately reducing radiosensitivity." (PMID 33931980, 2021). "Although other members of the HOX gene family, such as HOXA5, HOXA10, HOXB3, HOXB4, and HOXC618,19, have been found to be overexpressed in lung cancer tissues compared with normal tissues, little is known about the expression and biological function of HOXA4 in lung cancer." (PMID 29700285, 2018). "Also, in lung cancer, lncRNA LINC00461 enhanced radioresistance via miR-195/HOXA10." (PMID 35600868, 2022).
head and neck squamous cell carcinoma (10 papers, 2018 to 2022). A squamous cell carcinoma that arises from any of the following anatomic sites: lip and oral cavity, nasal cavity, paranasal sinuses, pharynx, larynx, and salivary glands. "HOXA10 suppression inhibited proliferation and enhanced apoptosis of head and neck squamous cell carcinoma cells." (PMID 36407869, 2022). "Homeobox A10 (HOXA10) has been regarded to serve as an oncogene in head and neck squamous cell carcinoma (HNSCC)." (PMID 33869744, 2021). "A previous study indicated that LINC00355 competitively binds to miR-195, resulting in the upregulation of HOXA10, thus promoting the progression of head and neck squamous cell carcinoma." (PMID 33111744, 2020). "However, miR-135a-5p is under-expressed in head and neck squamous cell carcinoma, which is closely related to the poor prognosis of the patients; miR-135a-5p overexpression targets HOXA10, thereby inhibiting tumor cell growth and promoting the apoptosis." (PMID 36228497, 2022). "Similarly, LINC00355 has been shown to act as an miR-195 sponge, thereby upregulating HOXA10 and promoting migration, invasion, and EMT in head and neck squamous cell carcinoma." (PMID 34095215, 2021).
leiomyoma (10 papers, 2013 to 2025). A well-circumscribed benign smooth muscle neoplasm characterized by the presence of spindle cells with cigar-shaped nuclei, interlacing fascicles, and a whorled pattern. "EPs and leiomyomas have also been found to exhibit similar decreases in HOXA10, which are frequently associated with hypermethylation of the HOXA10 promoter." (PMID 40305321, 2025). "The endometrial expression of HOXA10 was similar in areas overlying the leiomyoma compared with that in remote endometrial sites (2−ΔCt = 0.0224 vs. 0.0225)." (PMID 38524201, 2024). "The HOXA10 gene plays a major functional role in the endometrium, and its expression has been shown to be influenced by the presence of leiomyomas." (PMID 38524201, 2024). "Intramural leiomyomas appear to reduce of HOXA10, and possibly alter glycodelin levels in the secretory phase endometrium." (PMID 28620517, 2015). "After complementary deoxyribonucleic acid synthesis, HOXA10 expression was measured by quantitative polymerase chain reaction in the endometrium overlying and remote from the leiomyoma, as similar expression throughout the cavity was a prerequisite for the use of unguided biopsy method." (PMID 38524201, 2024). "In addition, we investigated the expression of HOXA10 in different locations of the uterine cavity using guided biopsies to evaluate spatially distinct effects of leiomyomas on endometrial gene expression." (PMID 38524201, 2024). "One previous study on women with submucosal leiomyomas showed similarly low expression levels of HOXA10 in the endometrium located directly over the leiomyoma and in the endometrium elsewhere in the cavity, suggesting that leiomyomas have a global effect on the endometrial transcriptomic profile." (PMID 38524201, 2024). "As all our subjects had fibroids this may explain why we demonstrated a reduced expression of HOXA10 mRNA from the secretory endometrium compared with proliferative phase at the PCR level although this was not reflected in protein expression." (PMID 28130434, 2017). "To determine whether myomectomy would reverse HOXA11 and HOXA10 expression, we evaluated the transcript levels of these genes in the endometrium of patients with intramural fibroid before and after myomectomy." (PMID 24639724, 2013). "In a study by Rackow and Taylor, HOXA10 was shown to be significantly reduced in submucosal fibroids compared to controls, and while patients with intramural fibroids had a trend towards lower HOXA10, the trend was not significant." (PMID 28620517, 2015). "Although underpowered, the study found a nonsignificant trend towards decreased HOXA10 in patients with intramural fibroids before myomectomy compared to after myomectomy." (PMID 28620517, 2015). "This study provides evidence that removal of intramural leiomyomas not affecting the expression pattern of HOXA10 and HOXA11 endometrial genes." (PMID 24639724, 2013). "Additionally, the endometrial expression of HOXA10 has been found to be decreased in women with leiomyomas compared with that in controls in most, but not all, studies." (PMID 38524201, 2024). "Because of the small sample size, statistical assessment of differences between the HOXA10 expression of different leiomyoma types could not be performed." (PMID 38524201, 2024).
oral cancer (9 papers, 2020 to 2025). "Overrepresentation analysis suggested HOXA10 was involved in the transcriptional misregulation contributing to the oral cancer phenotype." (PMID 35710803, 2022). "Also, MiR-494 inhibits the expression of the oncogene HOXA10 and thereby reduces the proliferation of oral cancer tissue cells." (PMID 36755291, 2023). "In contrast, HOXA7, HOXA10, HOXB7, HOXC6, HOXC10, HOXD10, and HOXD11 were consistently upregulated in potentially malignant oral lesions as they advanced to oral cancer." (PMID 41477365, 2025). "HOXA7, HOXA10, HOXB7, HOXC6, HOXC10, HOXD10, HOXD11 showed consistent upregulation in the potentially malignant oral lesions through their progression to oral cancer, which indicated the posterior prevalence of the HOX genes during cancer progression." (PMID 35710803, 2022). "In oral cancer, quercetin increases miR-16 expression levels, which in turn targets MMP-9, MMP-2 and HOXA10, so quercetin can prevent cell proliferation, migration, and survival in oral cancer." (PMID 35971151, 2022). "miR-494 repressed the expression of homeobox A10 (HOXA10) levels and was also observed to reduce the proliferation of oral cancer cells." (PMID 33806361, 2021). "Additionally, quercetin suppressed cell viability, migration, and invasion by regulating miR-16/HOXA10, which inhibits the expression of MMP-2 and 9 in oral cancer cells." (PMID 32050534, 2020).
endometrial polyp (6 papers, 2012 to 2025). A benign nodular lesion protruding above the surface of the endometrium. "Endometrial polyp-affected uteri showed a substantial decline in HOXA10 and HOXA11 messenger RNA levels compared to the controls, which may indicate decreased endometrial receptivity and impede implantation." (PMID 39941173, 2025). "HOXA10 (Fold change = 0.55, p = 0.149883): There is a decrease in HOXA10 expression in women with endometrial polyps, but this change is not statistically significant (p > 0.05)." (PMID 39915377, 2025). "HOXA10 and HOXA11 are downregulated in endometrial polyps, which may provide a molecular basis for reducing the pregnancy rate." (PMID 36246905, 2022). "Expression of HOXA10 and HOXA11 are shown to be decreased in endometrial polyps, which may provide a molecular basis for the decrease in pregnancy rates." (PMID 33079974, 2020). "Overall, the figure suggests that while PROKR1 and PROKR2 show the most significant changes, other genes like PROK1, PROK2, and HOXA10 exhibit smaller or non-significant alterations, highlighting the importance of certain prokineticins in the pathology of endometrial polyps." (PMID 39915377, 2025).
hepatocellular carcinoma (6 papers, 2020 to 2025). A malignant tumor that arises from hepatocytes. "SHP-1 inhibits HOXA10 and TGFβ2 which in turn regulates the expression of the migration-associated proteins, MMP2/9, and the migration of hepatocellular carcinoma cells." (PMID 38644382, 2024). "In hepatocellular carcinoma cells, HOXA10 knockdown induced cell cycle arrest at the G0/G1 phase and apoptosis by reducing the expression of Cyclin D1 and Survivin." (PMID 32296636, 2020). "In conclusion, this study identified and internally evaluated a five-gene metabolic signature (PLPPR1, CNTN3, HOXA10, HAGLR, and ENPP3) associated with immunotherapy response in hepatocellular carcinoma through integrative analysis of multiple transcriptomic datasets." (PMID 41515582, 2025). "For example, it has been found that HOXA10 was highly expressed in hepatocellular carcinoma." (PMID 35349479, 2022). "In addition, HOXA10 silencing suppresses the proliferation of hepatoma cells, induces cell cycle arrest and apoptosis by upregulating HDAC1 transcription, which was consistent with our findings." (PMID 33596966, 2021). "Moreover, there is evidence that HOXA10 could activate PI3K/Akt pathway in human hepatocellular carcinoma and chronic myelogenous leukemia." (PMID 33299465, 2020).
oral squamous cell carcinoma (6 papers, 2018 to 2025). "Recent studies have demonstrated that HOXA10 has been involved in regulation of proliferation, migration and invasion in oral squamous cell carcinoma." (PMID 29618950, 2018). "Similarly, HOXA10 promotes proliferation, migration and invasion in oral squamous cell carcinoma." (PMID 34294084, 2021). "HOXA10 is required for RUNX2 isoform II expression and cell proliferation in oral squamous cell carcinoma (OSCC)." (PMID 40498062, 2025). "HOXA10 promotes the expression of PRDX2 and inhibits ferroptosis in oral squamous cell carcinoma (OSCC)." (PMID 40498062, 2025).